TNF (tumor necrosis factor)
Diseases named in the same sentence as TNF in open-access papers (continued):
Sharing a sentence is not in itself a finding about the gene and the disease.
preeclampsia (continued). "According to our results, only the circulating levels of TNF-alpha and not those of IL-6 were enhanced in women with preeclampsia when compared to normotensive women." (PMID 21253506, 2010). "Circulating levels of the pro-inflammatory cytokines IL-6 and TNF-α, the chemokines IL-8, IP-10 and MCP-1, as well as the adhesion molecules ICAM-1 and VCAM-1, were raised in preeclampsia compared with healthy pregnancy, resulting in an overall pro-inflammatory systemic environment." (PMID 21126355, 2010). "TNF expression was absent in placental tissues during preeclampsia, while it was detected in the control, which may be due to depletion of the pro-inflammatory signal against the background of chronic inflammation or apoptosis of TNF-producing cells." (PMID 40647643, 2025). "In the preeclampsia group, the statistically most significant differences were found for the following markers in peripheral blood: increased levels of CD16+, CD56+, HLA-DR+, CD95+, and intracellular production of cytokines—IL-10, TNF, Perforin, GM-CSF, IGF, while reducing CD14+ levels." (PMID 40647643, 2025). "ELISA of pro‐inflammatory cytokines (TNF‐α, GM‐CSF) was not predictive for diagnosis of preeclampsia, and ratio of angiogenic markers sFlt‐1/PlGF was inadequate in the 1st and 2nd trimester in ruling out the possibility of preeclampsia but was highly accurate later in pregnancy." (PMID 38193120, 2024). "This study aimed at a comparative evaluation of pro-inflammatory (TNFα) and anti-inflammatory (CD206, MMP9, HGF) markers, as well as the levels of estrogen receptor α, expressed by decidual macrophages in normal pregnancy and in patients with early- and late-onset preeclampsia." (PMID 33672970, 2021). "Although in the in vitro model of acute exposure of cells to single high dose may not be a good representation of the in vivo situation, previous studies have reported that 100 ng/mL of TNF-α in cultured HUVEC enhanced endothelial cell activation, similar to that observed in preeclampsia." (PMID 32260307, 2020). "High levels of inflammatory cytokines such as IL-8 and TNFα in preeclampsia is correlated with the lack of Duffy expression which may contribute to increased neutrophil activation in the pathogenesis of preeclampsia." (PMID 32566660, 2020). "The presence of an elevated number of activated macrophages that secrete proinflammatory cytokines such as TNF-α may have negative effects in pregnancy, possibly inducing conditions including miscarriage, preterm labor, preeclampsia, and IUGR." (PMID 33036475, 2020). "TNF-alpha induces collagen I deposition in the maternal vasculature, and MMP1 and -7 activity induce extracellular matrix degradation, while CYP2J2, elevated in preeclampsia, may also be involved in uteroplacental and vascular remodeling." (PMID 31252672, 2019). "The role of TNF in the pathogenesis of preeclampsia is not yet fully understood." (PMID 29751529, 2018). "Because TNF-α may impair insulin signalling, inhibit lipoprotein lipase, induce PAI-1, and directly contribute to endothelial dysfunction, this cytokine may be involved in the pathogenesis of preeclampsia." (PMID 22523688, 2012). "In addition, IFN-γ could reverse the effects of TNF-α on EVT during metaphase invasion.There are no sensitive serum biochemical markers to predict preeclampsia." (PMID 36700203, 2022). "Pro-inflammatory cytokines, such as TNF-α, have been shown to have a direct negative effect on the function of Tregs, especially in cases of rheumatoid arthritis, and this may be an explanation for the altered levels of Tregs observed in preeclampsia." (PMID 30079067, 2018). "Furthermore, the activation of M1 macrophages by pro-inflammatory stimuli (TNF-α, IFN-γ, and bacterial LPS) inhibits trophoblast invasion that further contributes to the imbalance between Th1 and Th2 cytokines and the exaggerated inflammatory response observed in preeclampsia." (PMID 30079067, 2018).
preeclampsia (continued). "Our results showing no changes of maternal circulating TNF-alpha and a drop, but not a significant one, of IL-6 levels long after delivery suggest that the source of the excessive production of TNF-alpha in preeclampsia may be monocytes, neutrophils, and unlikely placenta itself." (PMID 21253506, 2010).
systemic inflammatory response syndrome (245 papers, 2005 to 2025). SIRS is a serious condition related to systemic inflammation, organ dysfunction, and organ failure. "Tumor necrosis factor (TNF) causes a lethal systemic inflammatory response syndrome (SIRS) which is characterized by significant metabolic alterations." (PMID 41132685, 2025). "Massive release of IL-2, IL-6, and TNF-α underlies the systemic inflammatory response syndrome (SIRS)." (PMID 41010851, 2025). "Elevated TNFα levels are known to be clinically associated with Systemic Inflammatory Response Syndrome (SIRS), leading to progression of hepatic encephalopathy, renal failure, and poor outcomes in patients with cirrhosis." (PMID 37828052, 2023). "TNF-α is regarded as a central mediator of immune regulation and of the pathophysiological changes associated with bacteremia and sepsis syndrome." (PMID 35563475, 2022). "In turn, loss of MLKL or RIPK3 protected mice from TNF‐induced systemic inflammatory response syndrome (SIRS)." (PMID 33314666, 2020). "However, excessive TNFα are associated with inflammatory cascade reactions by amplifying and exacerbating the inflammatory response and, in severe cases, triggering systemic inflammatory response syndrome." (PMID 37986083, 2023). "The hyperactive state of the EC is the consequence of the constitutive TNF-α production and has been linked to the hyperdynamic nature of systemic inflammatory response syndrome (SIRS) in neonates with the physiological trafficking of leukocytes to several organs and tissues." (PMID 36613805, 2022). "Finally, we show that oral administration of BHA protects mice from RIPK1 kinase-dependent lethality caused by TNF injection, a model of systemic inflammatory response syndrome." (PMID 34262020, 2021). "In this regard, Tat-Tg mice were more susceptible to the systemic inflammatory response syndrome caused by the intra-peritoneal injection of LPS, based on the evidence of increased lethality and expression levels of TNF-α, IL-1α, IL-6 and CXCL10 in the peritoneal lavages of surviving animals." (PMID 26343909, 2015). "Nec-1 treatment or RIPK3 deficiency also protected against TNF-α induced systemic inflammatory response syndrome (SIRS)." (PMID 37935670, 2023). "Mice with a knockin mutation in the UBA domain develop normally but are acutely sensitive to TNF-induced systemic inflammatory response syndrome (SIRS), which is caused by enhanced sensitivity to TNF-mediated cell death." (PMID 29452637, 2018). "TNF-α is a proinflammatory and procoagulative cytokine, and is associated with the development of systemic inflammatory response syndrome (SIRS) and further organ/tissue damage." (PMID 23894384, 2013). "Physiologically, IL-6 can cause the activation of leukocytes and promotion of TNF-α release and accounts for fever and leukocytosis present in systemic inflammatory response syndrome (SIRS)." (PMID 22655044, 2012). "Accordingly, it has been postulated that CS causes a systemic inflammatory response syndrome (SIRS) by the release of pro-inflammatory mediators like interleukin-6 (IL-6) and tumor necrosis factor alpha (TNF-α)." (PMID 22889197, 2012). "Treatment with Zharp1-163 in mice can alleviate TNF-α-induced RIPK1-driven systemic inflammatory response syndrome (SIRS)." (PMID 40877228, 2025). "Furthermore, in porcine ECMO models inducing systemic inflammatory response syndrome (SIRS), intestinal mucosal mast cells have been implicated in the rapid surge of TNF-α immediately following ECMO commencement." (PMID 39340702, 2025). "Given the established role of TNF-α in inducing necroptosis-driven inflammation, we evaluated the anti-inflammatory effect of Andro on TNF-α-induced systemic inflammatory response syndrome (SIRS) in mice." (PMID 40437958, 2025). "Furthermore, deferoxamine has been found to reduce the release of inflammatory mediators including IL-6 and TNF-α, thereby mitigating tissue damage caused by systemic inflammatory response syndrome (SIRS)." (PMID 41401162, 2025).
systemic inflammatory response syndrome (continued). "Despite its short half-life of approximately 20 minutes, TNF-α levels above 20 pg/mL predict systemic inflammatory response syndrome development with 85% sensitivity." (PMID 39981454, 2025). "TNF-α is considered a key member of the inflammatory cytokine family, playing a crucial role in initiating and driving nearly all aspects of the systemic inflammatory response syndrome." (PMID 40208318, 2025). "In the same way, IL-6 induces hepatic synthesis of acute phase proteins, and IL-1β and TNF-α participate in systemic inflammatory response syndrome and multiple organ failure." (PMID 40868835, 2025). "Activated cytokine signaling pathways, NF-κB signaling pathways and TNF signaling pathways can incite and expedite systemic inflammatory response syndrome." (PMID 39372399, 2024). "In general, IL‐6 and TNF‐α are involved in the pathogenesis of systemic inflammatory response syndrome." (PMID 38124471, 2024). "After activation, large amounts of TNF-α and IL-6 are released by monocytes, which results in systemic inflammatory response syndrome." (PMID 39200283, 2024). "TNF-α is considered the most important member of the inflammatory cytokine family because it initiates and propagates nearly all of the symptoms of the systemic inflammatory response syndrome." (PMID 38911245, 2024). "Moreover, mice with kinase-dead RIPK1 knock-in mutations are resistant to TNF-induced necroptosis and systemic inflammatory response syndrome (SIRS), similar to RIPK3 knockout mice, and demonstrate superior resistance compared to MLKL knockout mice." (PMID 39062098, 2024). "Inflammatory factors such as TNF, IL-1, and IL-6 contribute to a cytokine storm, resulting in tissue damage, severe systemic inflammatory response syndrome (SIRS), and multiorgan failure." (PMID 38957461, 2024). "Direct injection of TNF into mice can trigger systemic inflammatory response syndrome (SIRS) and animal death." (PMID 38789425, 2024). "IL-1β, IL-6, and TNF-α are common proinflammatory factors and are the most influential factors in the development of posttraumatic systemic inflammatory response syndrome (SIRS)." (PMID 37038178, 2023). "Once ALF progresses, inflammatory cytokines such as TNF-α and IL-6 are released into the bloodstream and activate inflammatory monocytes, leading to systemic inflammatory response syndrome (SIRS)." (PMID 37941897, 2023). "We then identified Ibrutinib as an inhibitor of RIPK3 and found that Quizartinib protected against the TNF-induced systemic inflammatory response syndrome in mice by inhibiting the activation of RIPK1." (PMID 37741898, 2023). "To evaluate the therapeutic effect of Vemurafenib on necroptosis-associated diseases in vivo, we utilized the TNFα-induced systemic inflammatory response syndrome (SIRS) mice model, which is a RIPK kinase-driven disease and strongly prevented by inhibiting necroptotic pathway." (PMID 37620300, 2023). "Progesterone improves sepsis syndrome by reducing inflammatory cytokines, IL-6 and TNF-α and by restoring the antioxidant defense system." (PMID 37077915, 2023). "A study based on a mouse model of systemic inflammatory response syndrome (SIRS) induced by D-galactosamine (D-GAL) combined with CpG ODN showed that sTLR9+ neutrophil can produce both TNF-α and IL-10 in the inflammatory site." (PMID 37724102, 2023). "Necroptosis is involved in various pathological conditions, including tumor necrosis factor (TNF)-mediated systemic inflammatory response syndrome (SIRS), ischemic reperfusion injury, neurodegeneration, and drug-induced tissue injuries." (PMID 36471162, 2022). "The release of such inflammatory mediators such as IL-6 and tumor necrosis factor-alpha (TNF-alpha) leads to systemic inflammatory response syndrome." (PMID 35740350, 2022).
systemic inflammatory response syndrome (continued). "This ongoing inflammation releases pro-inflammatory cytokines interleukin (IL)-1, IL-6, and IL-8 and systemic mediators such as tumor necrosis factor-alpha (TNF-α) leading to systemic inflammatory response syndrome (SIRS)." (PMID 35449658, 2022). "There are other small molecular inhibitors that target RIPK3 kinase activity and alleviate TNF-induced systemic inflammatory response syndrome." (PMID 35217652, 2022). "Their inhibitory effect on AURK was significantly reduced, and they performed better than Tozasertib in the TNF-induced Systemic Inflammatory Response Syndrome (SIRS) mouse model." (PMID 36249746, 2022). "Following brain injury, several cytokines, including TNF-α, IL-6, and CD11d, are released into circulation as part of the systemic inflammatory response syndrome (SIRS)." (PMID 36043003, 2022). "Next, we evaluated the potential protective effect of BHA in the acute model of systemic inflammatory response syndrome (SIRS) caused by intravenous injection of TNF, a lethal shock model previously demonstrated to originate from RIPK1 kinase-dependent cell death." (PMID 34262020, 2021). "Shenfu injection alleviated lung injury in a rat systemic inflammatory response syndrome model by inhibiting NF-B activation and decreasing the plasma level of IL-6 and TNF-α." (PMID 34393772, 2021). "Others, TNF-induced systemic inflammatory response syndrome, and even metastasis in cancer cells were also closely related to RIPK1 kinase activation." (PMID 34745415, 2021). "The cytokines, such as TNF-α and IL-1β, are closely relatedto the occurrence and development of systemic inflammatory response syndrome." (PMID 33503219, 2021). "In RIPK1- and RIPK3-dependent processes, necroptosis mediates TNF-induced systemic inflammatory response syndrome." (PMID 32366830, 2020). "We evaluated the potency of GNE684 in vivo using a model of SIRS (systemic inflammatory response syndrome) that is based on the administration of TNF plus zVAD." (PMID 31101885, 2020). "Problems arise when this unbalanced inflammatory response escalates and releases an excess of pro-inflammatory mediators such as IL-1, IL-6, IL-8, and TNFα, culminating in systemic inflammatory response syndrome (SIRS)." (PMID 32019485, 2020). "To confirm that the screening strategy leads to hits functionally active in vivo, we tested one of the hits for its ability to protect against RIPK-driven inflammation in TNF-α-induced systemic inflammatory response syndrome (SIRS)." (PMID 32123582, 2020). "SN-6109 was further tested in mice, showing efficacy against TNF-α-induced systemic inflammatory response syndrome." (PMID 32123582, 2020). "It has been described that cinnamaldehyde inhibits the IL-1β and TNF-α production of macrophages stimulated by LPS in vitro, as well as in systemic inflammatory response syndrome in vivo." (PMID 32759721, 2020). "In a mouse model of TNF‐induced systemic inflammatory response syndrome (SIRS), severe impact on intestinal epithelial cells (IECs) is observed." (PMID 32914580, 2020). "Necroptosis has been demonstrated in several animal models of diseases, such as renal and myocardial I/R injury, acute pancreatitis, skin and intestinal inflammation, LPS-induced lung injury, and TNF-induced systemic inflammatory response syndrome." (PMID 32082179, 2019). "In a previous study, RIP3-knockout mice were protected from LPS-induced lung injury and TNF-α-induced systemic inflammatory response syndrome." (PMID 32082179, 2019). "For example, TNF-alpha plays a key role in the development of systemic inflammatory response syndrome and can be lethal when produced at high levels." (PMID 29800728, 2018). "In the absence of a functional UBA domain, more active RIPK1 kinase accumulates in response to TNF, causing RIPK1 kinase-mediated cell death and systemic inflammatory response syndrome." (PMID 29452637, 2018).
systemic inflammatory response syndrome (continued). "Injections of TNF-α into experimental animals have been shown to bear a resemblance to the syndrome of septic shock, and infusion of recombinant TNF-α into humans has been shown to result in systemic inflammatory response syndrome." (PMID 30142934, 2018). "In the absence of a functional UBA domain of cIAP1, more active RIPK1 kinase accumulates in response to TNF, causing RIPK1 kinase-mediated cell death and systemic inflammatory response syndrome." (PMID 29452637, 2018). "There is a consensus as to a protective effect of IL-10 on the inflammatory action of TNF-α during systemic inflammatory response syndrome." (PMID 29357879, 2018). "Inflammatory cytokines, such as interleukins and TNFα, appearing in CS complicated by systemic inflammatory response syndrome, have also been advocated to stimulate ADM secretion." (PMID 28050899, 2017). "Nevertheless, both approaches indicate that RIPK1/RIPK3-mediated cellular damage by necrosis drives mortality during TNFα-induced systemic inflammatory response syndrome (SIRS)." (PMID 27048815, 2016). "TNFα-induced systemic inflammatory response syndrome (SIRS) is a systemic inflammation model mimicking acute inflammation caused by surgeries, bacterial infections, pancreatitis, and traumas in human patients." (PMID 27631783, 2016). "IL6, MCP-1, and TNFα have been defined by one author as being involved in “systemic inflammatory response syndrome”, while MIP1 and TNFα are more specifically associated with “neutophilic inflammation”." (PMID 24586996, 2014). "Systemic inflammatory response syndrome is characterized by increased serum levels of TNF-α, ICAM-1, E-selectin, IL-1β, and IL-6." (PMID 24369441, 2013). "Although the adverse events of the cytokines (IL6, IFN-γ, TNF-α) occurred, the concentrations of the released cytokines were much lower than adoptive T therapy method and the systemic inflammatory response syndrome was reversible." (PMID 24086580, 2013). "A randomized crossover study of 13 patients with AKI and the systemic inflammatory response syndrome found that CVVH for 24 hrs reduced plasma concentrations of TNFα and cleared more IL-6, compared to CVVHD." (PMID 23095370, 2012). "The systemic inflammatory response syndrome (SIRS), hallmark sign of sepsis, is characterized by a systemic inflammatory response with massive release of proinflammatory cytokines such as TNF-α, IL-1β, chemokines, nitric oxide, leukotrienes, reactive oxygen species." (PMID 22312472, 2011). "Numerous studies made on patients or animals with systemic inflammatory response syndrome of infectious origin, sustain the predictive potential of IL–6 and TNF alpha, which have the capacity to predict the evolution towards septic complications." (PMID 21776298, 2011). "Discussion: The study of IL–1 beta, IL–6 and TNF alpha blood dynamics, offers valuable information about the severity of a systemic inflammatory response syndrome in peritonitis." (PMID 21776298, 2011). "In the TNF-induced lethal shock model (a model for systemic inflammatory response syndrome), however, MTs seem to sensitize." (PMID 19727408, 2009). "Effects of CO administration on cytokine (TNF-alpha, IL-6, IL-1beta and IL-10) release were investigated in a porcine model in which a systemic inflammatory response syndrome was induced by endotoxin infusion." (PMID 18687112, 2008). "IL-10 reduces the release of TNF-α into the circulation which hinders the development of a systemic inflammatory response syndrome, and this correlates with an increase in survival." (PMID 18937852, 2008). "Finally, these results demonstrate that the combination of ethanol consumption and halothane exposure may enhance the possibility of the development of the sepsis syndrome, since increased systemic concentrations of TNF-α induced by endotoxin is a primary cause of that clinical condition." (PMID 15826301, 2005).